RNU6-214P (RNA, U6 small nuclear 214, pseudogene)
Gene: Small nuclear RNA gene on chromosome 6 (120,526,294 to 120,526,400, reverse strand). Ensembl gene ENSG00000206857.
Homologues: Orthologues: chimpanzee U6 (99% identical), macaque U6 (96% identical), guinea pig U6 (82% identical). Paralogues in human: RNU6-1316P (92% identical), RNU6-20P (92% identical), RNU6-1145P (91% identical), RNU6-128P (91% identical), RNU6-21P (91% identical), RNU6-25P (91% identical), RNU6-35P (91% identical), RNU6-38P (91% identical), RNU6-80P (91% identical), RNU6-891P (91% identical), RNU6-1 (90% identical), RNU6-1042P (90% identical), and 1287 more.